CDC20 (cell division cycle 20)
Diseases named in the same sentence as CDC20 in open-access papers (continued):
Sharing a sentence is not in itself a finding about the gene and the disease.
prostate carcinoma (continued). "Our data indicated that CDC20, an E3 ligase highly overexpressed in both prostate cancer and CRPC, negatively regulated the pyroptosis pathway by targeting GSDME for ubiquitination-mediated proteolysis in a degron-dependent manner." (PMID 37528490, 2023). "The analysis of multiple prostate cancer cohorts suggested that CDC20 was the most significantly over-expressed E3 ligase." (PMID 37528490, 2023). "Next, we sought to understand the role of the CDC20-GSDME interaction in the immune microenvironment in prostate cancer." (PMID 37528490, 2023). "Next, we sought to understand the role of CDC20 in the transcriptomic profile of prostate cancer by RNA sequencing (PRJNA882665)." (PMID 37528490, 2023). "To further confirm the role of CDC20 in prostate cancer, we found that the CDC20 protein abundance was positively correlated with the increased Gleason scores for prostate cancer based on a prostate cancer cohort of 102 cases." (PMID 37528490, 2023). "As an aberrant expression of E3 ubiquitin ligases can drive cancer progression, CDC20 was found to be the most significantly upregulated E3 ligase among multiple datasets during the screening of 883 human E3-ligases in prostate cancer." (PMID 37528490, 2023). "In order to confirm that the methyltransferase activity of KMT5A is important for the regulation of CDC20 expression in prostate cancer cell lines we used two molecules that have shown inhibitory activity against KMT5A, namely UNC0379 and Ryuvidine." (PMID 37509260, 2023). "Mechanistically, CDC20 enhanced ubiquitination-mediated GSDME degradation to prevent pyroptosis in prostate cancer cells, hence reducing intratumoral infiltration of CD8+ T cells." (PMID 38283351, 2023). "For instance, CDC20 promoted the self-renewal of prostate cancer stem-like cells via β-catenin trans-activation, thereby driving the prostate cancer progression." (PMID 35622386, 2022). "CDC20 has been reported to serve as an independent predictor for biochemical recurrence (BCR) in prostate cancer." (PMID 35360870, 2022). "Based on WGCNA module selecting and gene expression analysis, BUB1, KIF2C, CDC20, and PBK were eventually detected to be potentially associated with the clinical pathological features of prostate cancer." (PMID 35360870, 2022). "CDC20 promotes the progression of prostate cancer by stabilizing hypo-catenin in tumor-like dry cells." (PMID 33767726, 2021). "Then we generated stable cell lines with CDC20 knockdown in prostate cancer background with lentiviral shRNA virus." (PMID 34527589, 2021). "CDC20 overexpression facilitates the docetaxel resistance of the advanced castration-resistant prostate cancer cell lines." (PMID 34266348, 2021). "Our previous work has proved that targeting Cdc20 sensitized the docetaxel-resistant prostate cancer cells to chemotherapy." (PMID 34527589, 2021). "In keeping with that notion, as prostate cancer is androgen-dependent at the early stage, the combination of Cdc20 inhibitors with androgen inhibitors warrants further exploration." (PMID 34527589, 2021). "CDC6 and CDC20 have been reported to play critical roles in prostate cancer progression, and can serve as indicators for patient prognosis." (PMID 32922438, 2020). "CDC20 mediates the resistance to docetaxel in castration-resistant prostate cancer in a Bim-dependent manner." (PMID 32932732, 2020). "CDC20 was frequently overexpressed in malignant tumors, such as prostate cancer, hepatocellular carcinoma, and ovarian cancer." (PMID 31850052, 2019). "We analyzed 14 additional genes, including the AR-activated genes PSA, FKBP51, ORM1, STAG, Nkx3.1, FASN, AQP3, KLK2, and UGT2B; the AR-repressed genes DKK and FST; and the castration-resistant prostate cancer AR-regulated genes CDC20, CDK1, and UBE2C." (PMID 22761715, 2012). "Thus, the SPOP E3 ligase acts as a novel negative regulator of Cdc20, which in turn influences cell viability and apoptosis in prostate cancer." (PMID 40771930, 2025).
prostate carcinoma (continued). "SPOP is mutated in up to 15% of prostate cancers and these mutations have been shown to result in an inability of SPOP to associate with CDC20, preventing CDC20 protein turnover and consequently resistance to CDC20 inhibitors." (PMID 37509260, 2023). "CDC20 has been found to be overexpressed in a number of cancers, including prostate cancer, and there are a number of studies which demonstrate the relevance of CDC20 to prostate cancer development and progression." (PMID 37509260, 2023). "To confirm whether or not our in vitro findings could be translated into clinical specimens of prostate cancer, we interrogated publicly available datasets to confirm a positive correlation between CDC20 and KMT5A transcripts." (PMID 37509260, 2023). "Our study reported that the GSDME could be negatively regulated by an oncogenic protein, CDC20, in prostate cancer." (PMID 37528490, 2023). "CDC20 is also a critical prognosis factor for prostate cancer." (PMID 37528490, 2023). "Consequently, CDC20 inhibition improved the response to anti-PD-1 in murine models of prostate cancer." (PMID 38283351, 2023). "Furthermore, prostate cancer cell lines were evaluated via the next-generation RNA sequencing to assess transcriptomic profile upon CDC20 depletion." (PMID 37528490, 2023). "Even though known substrates of CDC20 are well documented for their roles in inhibiting prostate cancer development and progression, the exact molecular mechanisms by which CDC20 suppresses anti-tumor immunity in part by regulating pyroptosis have not yet been fully elucidated." (PMID 37528490, 2023). "Both SPOP mutation and CDC20 overexpression are important in docetaxel resistance with the inhibition or knockdown of CDC20 being able to resensitise cells to docetaxel highlighting the importance of CDC20 as a therapeutic target in prostate cancer at several disease stages." (PMID 37509260, 2023). "In addition, the protein abundance of CDC20 was negatively regulated by Cullin3SPOP complex, with SPOP being one of the most frequently mutated genes in prostate cancer." (PMID 37528490, 2023). "Furthermore, we demonstrate that KMT5A and CDC20 are positively correlated in clinical samples of prostate cancer." (PMID 37509260, 2023). "To further clarify the physiological role of CDC20 in regulating cell death, we identified the gasdermin protein GSDME as a novel ubiquitin substrate of CDC20 in the prostate cancer setting, which offers further molecular insights into its regulation of anti-tumor immunity." (PMID 37528490, 2023). "In addition, the high expression of CDC20 is significantly related to the advanced tumor stages of breast cancer, prostate cancer, colon cancer, and endometrial cancer." (PMID 35800227, 2022). "Silencing of CDC20 inhibited the growth of prostate cancer by decreasing β-catenin levels." (PMID 36056439, 2022). "In addition, similar to our results, previous studies on prostate cancer showed that CDC20 maintained the self-renewal ability of CD44+ prostate CSCs by promoting nuclear translocation and transactivation of β-catenin." (PMID 35800227, 2022). "However, besides its canonical role in cell cycle progression, the cell cycle-independent functions of CDC20 in prostate cancer remain largely unknown." (PMID 37528490, 2023). "Moreover, we demonstrate that depletion of CDC20 by shRNA constructs or small molecular inhibitors significantly enhances the anti-tumor immunity dependent on the existence of GSDME in prostate cancer and exhibits synergistic effects when combined with α-PD-1 therapy." (PMID 37528490, 2023). "Therefore, we conclude that KMT5A is a valid therapeutic target for the treatment of prostate cancer and CDC20 could potentially be utilised as a biomarker for effective therapeutic targeting." (PMID 37509260, 2023).
prostate carcinoma (continued). "Similar to our finding of the strong association between CDC20 and T helper 2 cells in HTLV-1 infected HCC, a published paper also stated that infection of human herpesvirus 8 induced the T helper 2 immune response which contributed to the formation and proliferation of prostate cancer." (PMID 35622386, 2022). "Moreover, the knockdown of CDC20 inhibits the clonic formation ability of prostate cancer cells." (PMID 34527589, 2021). "We retrieved the co-expressed gene list of each of CDC20, RRM2, and DTL across ADPC, CRPC, and NEPC cohorts, which showed 175, 92, and 159 genes significantly co-expressed with CDRs at different prostate cancer stages, respectively." (PMID 41492471, 2026). "Further mechanistic studies revealed that CDC20, DTL, and RRM2 were transcriptionally regulated by the RB1/E2F1 axis, mediating cell cycle progression in prostate cancer." (PMID 41492471, 2026). "This relationship between CDC20 and KMT5A is supported by a significant positive correlation between KMT5A and CDC20 transcripts in prostate cancer patients." (PMID 37509260, 2023). "More importantly, Apcin, a small molecular inhibitor that targets CDC20, exhibited synergistic effects with anti-PD1-based immunotherapy in murine models of prostate cancer." (PMID 37528490, 2023). "Additionally, cell division cycle 20 (CDC20), an E3 ligase upregulated in prostate cancer, downregulates pyroptosis via GSDME." (PMID 41291696, 2025). "Additionally, while CDC20, COL1A2 and S100A10 possess recognized pro-oncogenic activities, the precise roles of B4GALNT4 and NUAK1 in prostate cancer warrant elucidation." (PMID 39391236, 2024). "To further examine this hypothesis in prostate cancer cell models, we found that PC3, NCIH660, VCAP, and 22RV1 expressed CDC20 and GSDME at high levels with dataset from CCLE." (PMID 37528490, 2023). "Indeed, high expressions of CDC20, PLK1 and CDK1 correlate with prostate cancer occurrence and worse biochemical recurrence survival rates." (PMID 37509260, 2023). "With inhibitors for both CDC20 and KMT5A being developed, it would be important to determine whether or not they are able to synergise with each other in drug-resistant models of prostate cancer." (PMID 37509260, 2023). "CDC20 itself is a target for ubiquitination by the E3 ligase SPOP, which is commonly mutated and non-functional in prostate cancers, providing an explanation for elevated CDC20 levels." (PMID 37509260, 2023). "Our data showed that CDC20 expression is elevated in prostate cancer compared with normal prostates and is further upregulated CRPC following disease progression." (PMID 37528490, 2023). "In the genes of the MEmagenta module, we found that the known genes closely related to cancer stemness in non-prostate cancer, such as BRCA1, EZH2, FOXM1, CDC20, and CDCA8, were all clustered in this module, indicating these genes were also closely related to the stemness of prostate cancer cells." (PMID 33985534, 2021). "In addition, the combination of CDC20 and CD44 or β-catenin could be used as an important indicator of the prognosis of prostate cancer patients." (PMID 35800227, 2022).
hepatocellular carcinoma (39 papers, 2016 to 2025). A malignant tumor that arises from hepatocytes. "In hepatocellular carcinoma and bladder cancer, CDC20 is implicated in radio-resistance and proliferation." (PMID 40092489, 2025). "demonstrates that CDC20 may be an immune-associated therapeutic target in hepatocellular carcinoma because of its correlation with immune infiltration." (PMID 35515103, 2022). "High CDC20 expression allows cells with damaged DNA to escape mitosis and evade apoptosis, facilitating hepatocellular carcinoma development." (PMID 40387965, 2025). "A study in hepatocellular carcinoma showed that CDC20 and Rfc4 are involved in cancer cell survival, and another study showed that Rfc4 interacts with RPA1 for DNA replication and DNA damage repair." (PMID 39125953, 2024). "In line, the knockdown of CDC20 is a promising approach in treating different cancers, including lung, prostate, colorectal, hepatocellular carcinoma, and gastric cancers, as well as many other types." (PMID 39061186, 2024). "We found that CDC20 expression was significantly increased in hepatocellular carcinoma tissues and cell lines, and was correlated with histologic grade, pathologic stage, tumor status, and patient age." (PMID 35622386, 2022). "Ubiquitination of CCNA2 is associated with CDC20; the late promotion complex of ubiquitinated CCNA2 is activated by CDC20, and its overexpression is frequently observed in hepatocellular carcinoma and is a more recognized marker." (PMID 36479313, 2022). "In hepatocellular carcinoma, inhibition of CDC20 decreases cell proliferation in hepatocellular carcinoma cells." (PMID 36479313, 2022). "Of note, CDC20 also involves in the regulation of immune cell infiltration in certain cancers, such as hepatocellular carcinoma." (PMID 36034466, 2022). "Overexpression of CDK1, CCNB1 and CDC20 in tumor tissues predicted poor survival of patients with hepatocellular carcinoma." (PMID 34253236, 2021). "In hepatocellular carcinoma, the upregulation of CDC20 expression predicted a decline in overall survival and disease-free survival." (PMID 33912448, 2021). "CDC20 is highly expressed in hepatocellular carcinoma, which is recognized as a predictor of adverse clinical outcomes and an independent prognostic factor (Zhuang, Yang & Meng, 2018)." (PMID 32219041, 2020). "Notably, studies have shown that Cdc20 is highly expressed in the diseased tissues of most hepatocellular carcinoma samples." (PMID 39596644, 2024). "Furthermore, the up- regulation of CDC20 transcriptional and protein expression was confirmed in hepatocellular carcinoma cells HepG2 and SK-Hep1 compared with the normal liver cell L02 through qPCR and Western Blot." (PMID 35622386, 2022). "Recent literature has reported that CDC20 is highly expressed in pancreatic cancer, colon cancer, osteosarcoma cancer, lung adenocarcinoma, oral squamous cell carcinoma, and hepatocellular carcinoma." (PMID 32047816, 2020). "Genistein, the predominant isoflavone in soybean enriched foods, was reported to exert its anti-carcinogenic properties through inhibition of multiple genes including Cdc20 in primary glioblastoma, rhabdomyosarcoma, hepatocellular carcinoma and human embryonic carcinoma cells." (PMID 27626499, 2016). "Prior work in hepatocellular carcinoma (HCC) demonstrated that CCT4 physically interacts with Cdc20, a key activator of APC/C, and this interaction promotes the disassembly of the mitotic checkpoint complex (MCC) to activate APC/C." (PMID 41403933, 2025). "In addition, studies that focused on abnormal DNA methylation in hepatocellular carcinoma have also shown that patients with hypomethylation and high expression of CDC20 had shorter overall survival and that this gene served as a novel biomarker for precision diagnosis and treatment." (PMID 31289358, 2019).
hepatocellular carcinoma (continued). "Nevertheless, UDCA inhibited the expression of cell cycle-related genes and the repression effect was enhanced with a time increase (PLK1, UBE2C, BUB1, CDC20, BIRC5, p <0.001) in hepatoma cell lines SNU387." (PMID 38255993, 2024). "Several scientists pointed out that CDC20, CEP55, TRIP13, MYBL2 were overexpressed in hepatocellular carcinoma, compared with adjacent normal tissues." (PMID 38297250, 2024). "Following the synthesis of CCNB1, CDC20, CDC7, BUB1B, and MCM3 have been examined in hepatocellular carcinoma (HCC) samples." (PMID 36497125, 2022). "Adopting a series of bioinformatics analysis methods, the current study identified 763 DEGs and seven hub genes (CDC20, CDK1, MAD2L1, BUB1, BUB1B, CCNB1, and CCNA2) that may be involved in hepatocellular carcinoma tumorigenesis and progression." (PMID 33767726, 2021). "Using integrated bioinformatics analysis, CDC20 has been previously identified as a potential drug target for cholangiocarcinoma (CCA) and hepatocellular carcinoma (HCC)." (PMID 39061186, 2024). "In addition to CCNA2 regulating cell proliferation by binding with CDC20, CCNA2 is also regulated by CSN1 (signalosome subunit 1) in an ubiquitination-independent manner, which affects the proliferation and migration of hepatocellular carcinoma cells." (PMID 35954210, 2022). "Not surprisingly, among them, CDC20, CCNA2, and BUB1 are all associated with APC-related processes, which may be key nodes in the prognosis and occurrence of hepatocellular carcinoma." (PMID 36479313, 2022).